NF2 (NF2, moesin-ezrin-radixin like (MERLIN) tumor suppressor)
Diseases named in the same sentence as NF2 in open-access papers (continued):
Sharing a sentence is not in itself a finding about the gene and the disease.
cancer (continued). "This unique cancer type in the Tasmanian devil presents specific genomic alterations which can also be found in human SCHW and neurofibromas, pointing to a putative (NF2-dependent) role of WWC3 in these types of human cancer." (PMID 33467643, 2021). "Personalised treatments are lacking for MPM5, however recent insights into the inter-patient genomic heterogeneity of this cancer have revealed frequent somatic alterations involving the cancer genes BAP1, NF2 and CDKN2A6,7." (PMID 33741915, 2021). "An examination of publicly available (TCGA) human RNA-seq data, CNA, and methylation revealed that NF2 and TAOK1 are deleted and under-expressed, the GDI2 promoter is hypermethylated, and APC is lost in a subset of human cancers." (PMID 33808166, 2021). "Despite major genomic alterations in cancer driver genes (BAP1, NF2, CDKN2AB), mesothelioma is unfortunately characterized by low mutation rates." (PMID 34199066, 2021). "It is worth noticing that the number of cancer samples with SHANK2 amplifications way exceeds those with YAP1 amplification, FAT1 deletion, and NF2 deletion, indicating a previously unnoticed role of SHANK2 as a major oncogene." (PMID 34150758, 2021). "Although GTPBP4 has been most often found to act as an oncogene, it has also been described as a suppressor gene in rare cases, such as in neurofibromatosis 2 (NF2), suggesting that the role of GTPBP4 depends on the specific type of cancer." (PMID 33134380, 2020). "Our data were consistent with COSMIC in MPM, but were significantly different from COSMIC pan‐cancer data for BAP1 and NF2 (P = 0.008 and P = 0.004, respectively), suggesting specific mutation types for both genes in MPM." (PMID 32083805, 2020). "On the other hand, expression of tumor suppressor Drg1 and Nf2 was found to be elevated or decreased, respectively in the lungs of treated young or aged OVX mice at an advanced stage of cancer progression." (PMID 32887237, 2020). "Furthermore, in two recent studies screening germline cancer susceptibility mutations in large cohort of MPM patients, NF2, was not identified as a cancer susceptibility gene, suggesting that NF2 mutations observed in our series in unexposed patient are likely somatic." (PMID 32083805, 2020). "Interestingly, we identified a number of mutations in non-NF2 genes, including a hotspot TERTp c.−124: G > A mutation that may be related to poor prognosis and FGFR3 mutations that may represent biomarkers of a favorable prognosis as reported in other cancers." (PMID 31565188, 2019). "These genes belong to relevant intracellular signaling pathways in cancer such as PI3K-Akt (COL4A2, MYC, PDGFA, SPP1), proteoglycans (HIF1A, MYC, PLAUR, TGFB1), and Hippo (CTGF, MYC, NF2, TGFB1)." (PMID 29075357, 2017). "Our results are consistent with previous hypothesis that cytotoxic stresses (in our case, silica or asbestos) provide selective pressure and resistant clones against this pressure by genetic or non-genetic signaling alternation (RKIP reduced or NF2 mutated cells) would be founder of cancer." (PMID 25823924, 2015). "N-cadherin (N-cad), a key cell-matrix adhesion molecule and regulator of cancer cell migration, has not been studied in NF2-SWN." (PMID 41756440, 2026). "She lacked a family history of neurofibromatosis 2 (NF2) or cancer, as well as clinical or imaging evidence of NF2." (PMID 41199851, 2025). "To distinguish these two options, we introduced an NF2-KO using CRISPR/Cas9 into a variety of different cancer and non-cancer cell lines." (PMID 38879607, 2024). "In cancer, YAP/TAZ often gets activated through overexpression or the loss of upstream negative regulators, such as NF2, or non-genetically by a variety of upstream signals." (PMID 38607003, 2024). "While these molecules are moving steadily towards the clinic in MPM and other NF2 mutant cancers, we demonstrate that their applicability to other YAP/TAZ-driven cancers might be limited and requires further evaluation." (PMID 37400441, 2023).
cancer (continued). "In conclusion, our study reveals a novel iron metabolism-related mechanism in which LncRIM directly binds NF2 to trigger the activation of YAP and then promotes the expression of DMT1 and TFR1, which ultimately increases the cellular iron level and promotes cancer cell proliferation." (PMID 37080959, 2023). "Notably, both integrins and cell-cell adhesion receptors can modulate upstream components in the Hippo pathway, such as NF2 and LATS1/2, leading to YAP activation in cancer cells." (PMID 38125873, 2023). "Our results further revealed that upregulating MAPK8IP1P2 activated Hippo signaling by disrupting the repressive effect of miR-146b-3p on NF2, RASSF1, and RASSF5 expression by sponging miR-146b-3p as ceRNA, which further suppressed anoikis resistance in thryoid cancer cells." (PMID 33489905, 2020). "DNA hyper-methylation at NF2 and KIBRA promoter mediated by MOC2 and DNMT3a complexes suppresses their gene expression and Hippo signaling pathway activation, which further promotes HCC cancer stemness and tumorigenesis." (PMID 33234142, 2020). "Furthermore, interrogation of signaling partners in the NF2 cascade revealed high levels of PAK1, an upstream oncogene that inactivates NF2 in cancer cells through phosphorylation." (PMID 28552950, 2017). "Although the role of merlin inactivation has not been well characterized in these other cancers, NF2 status may be relevant for prognosis and future chemotherapeutic approaches." (PMID 38336988, 2024). "To date, there have been no reports on the use of NF2 as a prognostic factor in cancer." (PMID 33818013, 2021). "Given that loss-of-function mutations and reduced NF2 expression are frequently observed in human cancer, it is interesting to speculate that the CRL4DCAF1-LATS axis might be a potential target for cancer treatment, especially for a subset of patients with NF2 lesions." (PMID 29673168, 2018). "In the 78 CNS tumors with histologies not included in prior pediatric pan-cancer analyses, the recurrently altered genes uniquely containing oncogenic alterations (compared to the common tumors) were CTNNB1, NF2 and KIT." (PMID 38992034, 2024). "The role of a CRUMBS/WWC or a NF2/WWC protein complex in tumor growth and cancer has not been analyzed yet." (PMID 33467643, 2021). "Data from the Catalogue of Somatic Mutation in Cancer (COSMIC) census show that Hippo pathway genes, with the exception of NF2 and TAZ, are not cancer-related genes." (PMID 28035075, 2017). "Next, we examined several cancer-related signaling pathways in the NF2 LOF mutants-transduced MCF10A cells and found that expressing the NF2 LOF mutants did not affect the activation of YAP, AKT or ERK but largely enhanced the phosphorylation of JNK and its substrate c-Jun." (PMID 39572544, 2024).
genetic disorder (24 papers, 2017 to 2026). "Neurofibromatosis type 1 (NF1) and NF2-related schwannomatosis (NF2-SWN) are distinct genetic disorders caused by pathogenic variants in the nf1 and nf2 genes, respectively." (PMID 40510571, 2025). "NF2 is a complicated neuro-cutaneous genetic disorder that can cause considerable morbidity." (PMID 33445724, 2021). "Preservation and restoration of function have increasingly moved into the focus of attention in the treatment of patients with neurooncological diseases, especially in those with hereditary genetic diseases such as NF2." (PMID 39762911, 2025). "In summary, NF2-related SWN is a complex genetic disorder characterized by the presence of various tumors affecting the central and peripheral nervous systems." (PMID 39618887, 2024). "The most well-known genetic disorder associated with familial cardiac schwannomas is neurofibromatosis type 1 (NF1), and type 2 (NF2)." (PMID 37240461, 2023). "We achieved disease control with everolimus (mTOR inhibitor) and bevacizumab (anti-VGEF antibody) in our patient #13 with NF2, showing the importance of targeted therapies in genetic disorders." (PMID 38139220, 2023). "Because our patient did not have a family history of genetic disorders, it is likely that he had a new mutation resulting in NF2." (PMID 40713130, 2025). "NF2 is an inherited genetic disorder that is characterized by VSs as its main presentation." (PMID 39618887, 2024).
benign tumors (19 papers, 2009 to 2025). "Loss of NF2 induces the formation of neurofibromatosis II and benign tumors, and truncating mutations in Lats2 and NF2 are evident in non-VHL-mutated ccRCC." (PMID 39123485, 2024). "These benign tumors typically result from loss of the neurofibromatosis type 2 (NF2) tumor suppressor gene." (PMID 21454924, 2011). "Neurofibromatosis type 2 (NF-2) is an autosomal-dominant disorder resulting from germline/mosaic variants in the neurofibromin 2 (NF2) tumor suppressor gene, leading to multiple benign tumors in the nervous system and along peripheral nerves." (PMID 39415595, 2024). "The present study represents by far the largest series of NF2 patients to the best of our knowledge that have undergone radiation treatment for the benign tumors that occur in the condition." (PMID 37051330, 2023). "At this stage, investigation of NF-2 gene status in MPMNs is interesting, although these are characteristically incidentally detected benign tumors." (PMID 30542514, 2018). "Cases were NF2 patients treated with radiation for benign tumors." (PMID 37051330, 2023). "Although the efficacy of peptide vaccination alone for malignant diseases has thus far proved to be limited, it may have the capacity to slow the growth of benign tumors, including those in NF2 patients." (PMID 31848332, 2019). "Interestingly, we have recently shown in another NF2-related benign tumor, meningiomas, that let-7d, let-7b, and let-7g are also upregulated as compared to the arachnoidal tissue of origin." (PMID 21454924, 2011). "Although studies with a larger number of NF2 patients are warranted to confirm the findings of this study, the results suggest that this immunotherapeutic strategy may be favorable in patients with benign tumors such as NF2." (PMID 31848332, 2019). "NF2 patients should not be offered radiotherapy as first-line treatment of benign tumors and should be given a frank discussion of the potential 5% excess absolute risk of M/MP." (PMID 37051330, 2023).
CNS tumors (16 papers, 2006 to 2026). "The finding that merlin regulates SC NPC growth in a Rac1- and ErbB2-dependent manner firmly establishes a central growth control target for NF2-associated spinal ependymoma, and advocate for further studies addressing the potential use of ErbB2 inhibitors to treat these CNS neoplasms." (PMID 24817309, 2014). "Magnetic resonance imaging revealed multiple central nervous system tumors, confirming the diagnosis of NF2." (PMID 40821302, 2025). "Eight patients had multiple central nervous system tumors at first presentation, seven of whom had NF2." (PMID 22543431, 2012).
nervous system tumors (16 papers, 2004 to 2026). "Patients with NF2 develop multiple tumors in the nervous system, and NF2-associated tumors often contribute to earlier-than-expected death." (PMID 31591325, 2019). "Mutations of NF2 are frequently observed in tumors of the nervous system." (PMID 29709009, 2018). "At present, there are many studies on NF2 protein in nervous system tumors." (PMID 32337368, 2020).
autosomal dominant disease (9 papers, 2009 to 2022). Autosomal dominant form of disease. "NF2 is an autosomal dominant disease with usually a 50% risk of transmission from an affected individual to their offspring." (PMID 19545378, 2009). "NF2 is an autosomal-dominant disease caused by a biallelic loss of the NF2 gene on chromosome 22." (PMID 35628268, 2022). "NF is an autosomal dominant disease with two distinct forms, NF1 and NF2." (PMID 25295078, 2014).
neurological diseases (8 papers, 2018 to 2026). "The most common reasons to perform an MRI on a HI recipient were for monitoring NF2, neurological diseases, and for muscloskeletal/injury investigation." (PMID 33788034, 2021). "Meanwhile, the core genes in the Lean line might be Nf2 (linking syndromic, nervous, urinary and cellular proliferative diseases), Lrp1 (linking cardiovascular and nervous system diseases and physical disorders), and Ifngr2 (linking immune, endocrine and metabolic diseases)." (PMID 36414820, 2023).
peripheral neuropathy (6 papers, 2012 to 2025). A disorder affecting the peripheral nervous system. "Previous studies investigating peripheral neuropathies after loss of NF2 gene expression demonstrate important roles for the merlin protein, including neuronal growth and regeneration." (PMID 40895102, 2025). "Patients with NF2 may present with distinctive “plaque-like” cutaneous schwannomas, ophthalmologic findings, or neurologic deficits such as hearing loss or peripheral neuropathies which may prompt further radiologic or genetic evaluation." (PMID 31161239, 2020). "Epidemiologic studies have revealed that NF2-patients frequently present with peripheral neuropathies." (PMID 31161239, 2020). "Most affected individuals will develop damage to peripheral nerves (peripheral neuropathy) in their lifetime, another common clinical feature in NF2." (PMID 25012216, 2014). "Another investigation, with primary focus on NF2-related neuropathy, found that clinical signs manifesting as peripheral neuropathy occurred in 47% of investigated patients." (PMID 25012216, 2014). "Besides the development of multiple gliogenic tumors affecting both the PNS and CNS, many NF2 patients will develop peripheral neuropathy during their lifetime." (PMID 25012216, 2014). "Furthermore, by determining nerve conduction properties, two studies were able to show that NF2-related peripheral neuropathy is commonly of axonal origin." (PMID 25012216, 2014). "Furthermore, 60% of NF2 patients suffer from peripheral nerve damage, clinically referred to as peripheral neuropathy." (PMID 25012216, 2014).
infection (5 papers, 2011 to 2024). The state of being infected such as from the introduction of a foreign agent such as serum, vaccine, antigenic substance or organism. "In the late stages of infection of the PI group and at the early and late stages of infection in the RI groups, extensive necrotizing/hemorrhagic foci (NF2) were found in the vicinity of enlarged bile ducts, some containing adult flukes, suggesting parasites may have caused NF2 while feeding." (PMID 38929451, 2024). "Infections initiated with thesame amount of PYΔpy01365(NF1) orPYΔpy01365(NF2) resulted in a delay in host death as comparedto YM." (PMID 21625465, 2011). "Inhibition of SGK1 was performed using lentiviral SGK1-shRNA infection in Ben-Men-1 cells, or with the SGK1 inhibitor GSK650394 in both Ben-Men-1 cells and NF2-shRNA ACs." (PMID 26219339, 2015).
neoplastic disorder (2 papers, 2012 to 2025). "Schwann cells are vital to development and maintenance of the peripheral nervous system and their dysfunction has been implicated in a range of neurological and neoplastic disorders, including NF2-related schwannomatosis (NF2-SWN)." (PMID 40585242, 2025).
neurodegenerative disease (2 papers, 2022 to 2025). A disorder of the central nervous system characterized by gradual and progressive loss of neural tissue and neurologic function. "Ex: whole brain RT, NF2, neurodegenerative disease, did not speak Dutch." (PMID 40011234, 2025).
cardiac disease (1 paper, 2020). "Using gain- and loss-of-function genetic models, it was shown that the Hippo-YAP signaling pathway components Mst1/2, Sav1, Lats1/2, NF2, and downstream transcriptional regulators YAP and Tead1 regulate cardiac gene expression, cardiomyocyte proliferation, and cardiac disease status." (PMID 32938943, 2020).
gastrointestinal disorders (1 paper, 2025). "While distinct from NF1, an association between NF2 and gastrointestinal disorders has not been reported." (PMID 40247846, 2025).
NF2 also shares sentences with these, for which no sentence is quoted: peripheral nervous system tumors (8 papers); medulloblastoma (5); Anxiety (4); clear cell renal cell carcinoma (4); ependymal tumor (4); anaplastic meningioma (3); Carney complex (3); fibrosarcoma (3); Li-Fraumeni syndrome (3); lung squamous cell carcinoma (3); Pleural effusion (3); renal carcinoma (3); Transitional Meningioma (3); cervical cancer (2); cervical squamous cell carcinoma (2); chondrosarcoma (2); Cirrhosis (2); Cowden syndrome (2); Duchenne muscular dystrophy (2); Ewing sarcoma (2); Hearing impairment (2); hereditary hemorrhagic telangiectasia (2); Legius syndrome (2); low grade glioma (2); Lynch syndrome (2); multiple endocrine neoplasia (2); nasopharyngeal carcinoma (2); neuroblastoma (2); optic pathway glioma (2); papillary renal cell carcinoma (2).
A further 120 diseases each share a sentence with NF2 in 2 papers or fewer.